BDNF (brain derived neurotrophic factor)
Diseases named in the same sentence as BDNF in open-access papers (continued):
Sharing a sentence is not in itself a finding about the gene and the disease.
depression (continued). "In addition, depression inhibits brain-derived neurotrophic factor (BDNF), one of the factors associated with neuronal resilience." (PMID 37096248, 2023). "Stimulation with LIFUS on either the prefrontal cortex or the ventromedial prefrontal cortex (vmPFC) attenuated the depressive behaviors of depressed model rats, accompanied by enhanced brain-derived neurotrophic factor (BDNF) levels, whose downregulation is closely linked with depression." (PMID 36970512, 2023). "This study offers promising (though early) evidence that BDNF may be a useful biomarker of HIV-associated depression, with further work necessary to replicate this finding in diverse cohorts." (PMID 37693812, 2023). "BDNF is widely expressed in the brain, and its dysregulation has been implicated in the pathophysiology of numerous neurological and psychiatric disorders, such as depression, Alzheimer's disease, and substance use disorders." (PMID 37845289, 2023). "Dysregulation of the HPA axis has been observed in both depression and obesity, which may partially be caused by decreased brain-derived neurotrophic factor (BDNF)." (PMID 37892388, 2023). "Additionally, inflammation reduces BDNF secretion and hippocampus neurogenesis, both of which are frequently associated with depression." (PMID 37764744, 2023). "While searching for potential mechanisms of action, we examined brain monoamine and BDNF levels, which are consistent with the underlying hypotheses of depression-like behaviors." (PMID 37908978, 2023). "Similarly, more recent meta-analyses (n = 21,060) show a relationship between stress and depression with the Val66Met BDNF polymorphism." (PMID 37242525, 2023). "Indeed, studies have suggested that decreased BDNF levels can be associated with depression onset and progression." (PMID 37109038, 2023). "Another study showed that low plasma BDNF is associated with suicidal behavior in major depression." (PMID 37108261, 2023). "Notably, central administration of a recombinant BDNF protein causes a prolonged improvement of depression-like behavior in ASC mice." (PMID 37761014, 2023). "Furthermore, increased DNA methylation levels of the BDNF gene have been linked to depression in the general population." (PMID 38249586, 2023). "Studies on LM’s impact on mood are limited, especially acute designs such as the current investigation, but one pilot study showed that H. erinaceus decreased depression, anxiety, and sleep disorders with an associated elevation in peripheral levels of pro-BDNF over an 8-week treatment period." (PMID 38140277, 2023). "The association between BDNF and major depressive disorder is the subject of extensive research." (PMID 37631295, 2023). "While BDNF downregulation has been directly associated with brain neurological conditions such as depression, Huntington’s disease, and Rett syndrome, proBDNF secretion inhibits synapse formation, dendritic arborization, and impairs synaptic transmission and plasticity." (PMID 37238659, 2023). "Besides, it was found that low levels of BDNF were associated with low drug response in major depressive disorder (MDD)." (PMID 37252132, 2023). "Thus, the augmentation of BDNF expression via gut bacteria is effective for improving anxiety- and depression-associated behaviour." (PMID 36834953, 2023). "Downregulation of BDNF expression, which is associated with decreased adult hippocampal neurogenesis, occurs in brains of older adults with decreased learning ability and those of patients with major depressive disorders." (PMID 36834953, 2023). "Treatments for controlling those issues might be made available if a BDNF gene mutation is linked to a neurological or psychiatric illness such as schizophrenia or depression." (PMID 38015338, 2023). "Nevertheless, the neurotrophic hypothesis of depression relies heavily on the connection between reduced levels of BDNF and an increased occurrence of depression and associated features." (PMID 37631295, 2023).
depression (continued). "The neurotrophic hypothesis proposes that a decrease in BDNF is implicated in the pathophysiology of depression, while an increase in BDNF is essential for the therapeutic effect of antidepressants." (PMID 37492530, 2023). "While the molecular aspects of major depressive disorder are not fully understood, they are believed to involve deficiencies in neurotransmission, reduced levels of BDNF, genetic factors, the immune system, and hormonal imbalances, as well as environmental factors." (PMID 37631295, 2023). "Additionally, an increase in IL-6 and TNFα, and a decrease in BDNF have often been associated with anxiety and depression in patients as well as in experimental models." (PMID 37530884, 2023). "The present results support the hypothesis that BDNF may be a suitable marker for chronic stress, which causes depression." (PMID 36834565, 2023). "Furthermore, anxiety, depression risk, neuroticism, and serotonergic neurotransmission have all been linked to altered serum BDNF levels and BDNF gene polymorphism." (PMID 36986674, 2023). "The “neurotrophin hypothesis of depression” has been confirmed: “Robust empirical findings indicate an association between increased BDNF gene expression and peripheral concentration with improved neuronal plasticity and neurogenesis”." (PMID 39484176, 2023). "Decreased BDNF levels are believed to be a direct cause of depression." (PMID 37828015, 2023). "Finally, we reviewed the evidence that relates peripheral levels of BDNF and BDNF polymorphisms with the development and management of treatment-resistant depression." (PMID 37834258, 2023). "Certain reports revealed that Val66-Met polymorphism in the BDNF gene may be a significant genetic predisposition for depression." (PMID 36751189, 2023). "Furthermore, smaller hippocampal volumes in drug-naïve patients with first episode psychosis (and depression) are associated with lower BDNF levels." (PMID 37712092, 2023). "Finally, the reduced expression of BDNF precipitates higher susceptibility to stress-induced oxidative damage, indicating an interplay between these depression-related parameters." (PMID 37108052, 2023). "The present results showed that MSD decreased the protein expression levels of BDNF and TrkB in the elderly offspring, which further supports that decreased expression of BDNF and TrkB may be a potential cause of depression and cognitive impairment." (PMID 37168717, 2023). "BDNF deficiency in the amygdala is visible in women with major depressive disorder (MDD)." (PMID 37089920, 2023). "In addition to studies involving serum BDNF levels, several studies reveal the connection between a BDNF polymorphism, Val66Met, to depression." (PMID 37242525, 2023). "Thus, BDNF appears to play an important role in the underlying mechanisms of depression, according to several studies." (PMID 37631295, 2023). "Their findings align with ours, as they reported a strong association between these activities and a reduced risk of depression, improved mental health, increased BDNF levels, reduced memory impairment, enhanced quality of life (QOL), improved fitness, and other physiological parameters." (PMID 37422660, 2023). "From the cross-sectional studies reported in this review, it appears that there is a possible association between low BDNF levels and depression and CVD as concurrent conditions, but prospective studies are needed to determine a possible cause–effect relationship." (PMID 37895349, 2023). "Similarly, increased BDNF methylation was associated with suicidal ideation and depression one year after breast surgery in women with breast cancer." (PMID 38069051, 2023). "The association between BDNF and depression was highlighted at the molecular level." (PMID 36751189, 2023).
depression (continued). "This review article aims to comprehensively overview the significance of single nucleotide polymorphisms (SNPs) in BDNF/BDNF-AS genes within psychiatric conditions, with a specific focus on their associations with depression, schizophrenia, and bipolar disorder." (PMID 37763162, 2023). "Interferon-alpha has also been reported to cause reduced serum brain-derived neurotrophic factor levels, which may contribute to the mechanism underlying depression." (PMID 36711294, 2023). "Similarly, BDNF plays a crucial role in neuronal growth and plasticity, and reduced levels have been linked to depression." (PMID 37997979, 2023). "Similarly, the decreased expression of NGF and BDNF in our study was confirmed by clinical and animal studies, in which it has been suggested that depression is associated with the neuronal atrophy caused by low levels of neurotrophins in the hippocampus." (PMID 36835228, 2023). "The alteration of BDNF levels, as well as the imbalance between pro-BDNF and m-BDNF, and deficits in BDNF signaling are associated with the pathogenesis of various neurologic and psychiatric disorders, including depressive disorder, schizophrenia, and bipolar disorder." (PMID 37763162, 2023). "In addition to BDNF, its receptor TrkB is implicated in depression disorders and the therapeutic effects of antidepressant drugs." (PMID 36142808, 2022). "Interestingly, oxytocin and BDNF are both implicated in the pathophysiology of depression, schizophrenia, anxiety, and cognition." (PMID 35721318, 2022). "Finally, the rs6265 polymorphism of BDNF was found in two studies to be associated with depression among breast cancer patients." (PMID 35528795, 2022). "The reduction of the neuroprotective function of BDNF may in part explain the association with these clinical features, shared between depression and FM." (PMID 35344113, 2022). "A reduced activity of the BDNF downstream signaling pathway induces susceptibility to depression in rodents, whereas activation of this pathway causes antidepressant-like effects in animal models of depression." (PMID 36014820, 2022). "Increased levels of inflammatory cytokines are also suggested to reduce levels of an important neurotrophic factor, Brain Derived Neurotrophic Factor (BDNF), which is hypothesised to be another key mechanism underlying development of depression." (PMID 34920399, 2022). "This inhibition of ACE2 and subsequent decrease in BDNF leads to neurodegeneration and may cause mental disorders such as anxiety, depression, and cognitive impairment." (PMID 35444632, 2022). "In addition, C/EBPβ was highly activated and its downstream BDNF was heavily repressed in susceptible group, suggesting the important role of C/EBPβ in depression." (PMID 36578534, 2022). "Serum BDNF levels before treatment have been associated with SSRI response in depression." (PMID 36572893, 2022). "Furthermore, studies have also investigated methylation of BDNF promoter I in major depressive disorder, showing an association between neurocognitive performance and two BDNF SNPs, while methylation levels mediated this effect at specific sites of promoter I." (PMID 35836661, 2022). "It is therefore likely that research on the association between depression and BDNF may continue to be emphasized in the future." (PMID 36291673, 2022). "Moreover, it also induces neurochemical changes associated with depression, e.g., brain-derived neurotrophic factor (BDNF) and proinflammatory cytokines, which are significantly altered in the serum of depressive patients." (PMID 35626632, 2022). "A recent study found that serum BDNF levels were lower in SLE patients with depressive symptoms than in HC, which raises the possibility that serum BDNF levels could serve as a reliable biomarker of depression risk in SLE patients." (PMID 36506019, 2022).
depression (continued). "Depression is a mood disorder characterized by an importunate feeling of unhappiness and loss of interest and is directly allied with brain-derived neurotrophic factors (BDNF) and neuroinflammation." (PMID 36014565, 2022). "Results of the study suggest that BDNF and proBDNF may be associated with symptoms of insomnia and depression in patients with OSA." (PMID 36498709, 2022). "Thus, regular physical exercise reduces stress induced loss of BDNF levels and can alleviate depression, anxiety and improve mood." (PMID 35492581, 2022). "In addition to neurogenesis as a part of neuroplasticity related to BDNF in the brain, synaptic plasticity is also associated with depression." (PMID 36014336, 2022). "In addition, our data showed that AD induced plasticity-related changes in the reward circuits that are associated with a depression-like phenotype, as reflected by elevations in pCREB, ΔFosB, and BDNF protein levels." (PMID 36088447, 2022). "Although the association between BDNF and depression risk factors was lost in the presence of elevated levels of a major inflammatory marker (IFN-γ), the detection of this link is novel as was the association with miRNAs related to atherothrombosis and depression." (PMID 35911513, 2022). "Additionally, BDNF has been implicated in a variety of brain disorders, including depression, PTSD, schizophrenia, Parkinson’s disease, and autism spectrum disorders amongst many more." (PMID 35732627, 2022). "Moreover, the decreased BDNF and increased inflammatory pattern have been already associated with depression." (PMID 36498925, 2022). "Depression is known to be associated with the BDNF/TrkB/ERK/CREB signaling pathway." (PMID 36614066, 2022). "In this study, we evaluate possible changes in BDNF levels in people, both healthy controls and patients suffering from mental disorders, such as schizophrenia, cognitive impairment of various causes, depression, and obsessive-compulsive disorder (OCD), following psychotherapy." (PMID 36672535, 2022). "Depression downregulates hippocampal BDNF showing a neuronal loss." (PMID 36211101, 2022). "High cortisol concentrations not only induce behavioral changes such as depression and anxiety, but also cause pathological damage to hippocampal neurons, reducing the production of neurogenic factors such as brain-derived nerve growth factor (BDNF)." (PMID 36614066, 2022). "BDNF is associated with the neurobiology of depression and antidepressant effects." (PMID 36761172, 2022). "Furthermore, decreased BDNF concentration in late pregnancy has been associated with increased risk of depression, and lower BDNF concentration has been reported in mothers with PPD compared to mothers without depressive symptoms." (PMID 34989854, 2022). "In addition to schizophrenia, altered levels of BDNF in the hippocampus and blood have been associated with other psychiatric disorders, including depression." (PMID 35757201, 2022). "Furthermore, emerging evidence from animal studies demonstrated that the exercise-elicited AMPK/BDNF pathway plays a crucial role in modifying diseases, such as depression, memory deficiency, and AD44–46." (PMID 35732806, 2022). "It has also been shown that the epigenetic regulation of the BDNF gene may be involved in setting the risk for psychiatric and affective disorders, such as depression and anxiety." (PMID 35911240, 2022). "Although the neural circuitry underlying depression remains incompletely understood, depression could reduce BDNF levels in specific brain regions such as the hippocampus and prefrontal cortex." (PMID 35565814, 2022). "The evidence that modulation of the BDNF-depression association occurs primarily at low IFN-γ levels suggests that under elevated inflammatory conditions, as found, e.g., in severe obesity, the ability of BDNF to impact on depressive symptoms is potentially negligible." (PMID 35911513, 2022).
depression (continued). "Among patients not using psychotropic medications, significant positive associations were seen between BDNF and most symptom clusters; depression, somatization, interpersonal sensitivity, anxiety, phobic anxiety, and psychoticism, as well as a global severity index were found." (PMID 35114967, 2022). "Besides, proteomic analysis of animal models of depression found that, the levels of alpha crystallin B (Cryab) and brain-derived neurotrophic factor (BDNF) of sHSP family members decreased, can explain the loss of some neurons during ferroptosis." (PMID 35478955, 2022). "This intervention study demonstrated that L. casei could significantly protect against depression in rats, which was possibly associated with alterations in the gut microbiota composition and the mediation of BDNF–TrkB signaling." (PMID 36499295, 2022). "Furthermore, a decrease in BDNF levels was associated with increased values of miR-132 and miR-182 in patients with depression; suggesting a potential role of serum BDNF and its related miRNAs as diagnostic biomarkers." (PMID 35916975, 2022). "Increased neuroplasticity of BDNF is implicated in neurotrophic theories of depression and its treatment since there is robust evidence that serum BDNF concentrations are decreased in depressed individuals and that antidepressant treatment regulates its levels." (PMID 35837277, 2022). "However, a BDNF/TrKB signaling dysfunction can impair synaptic transmission and cause depression-like behaviors." (PMID 36578534, 2022). "Under long-time exposure to stressful conditions, glucocorticoid hormones may cause depression via the regulatory effect of miR-124 on BDNF." (PMID 35916975, 2022). "The neurotrophic hypothesis of depression posits that chronic stress is associated with a reduction in BDNF and the resulting atrophy of neurons in brain regions associated with this disease." (PMID 35888708, 2022). "The brain-derived neurotrophic factor (BDNF) has been implicated in depression." (PMID 35624812, 2022). "Vitiligo is associated with the depression and is closely linked with lower BDNF levels." (PMID 35508633, 2022). "The loss of BDNF has also been suggested as a contributory factor to the progression of PD, AD and Huntington’s disease, as well as to conditions such as depression." (PMID 35890231, 2022). "Since it is well-established that reduced BDNF levels in the brain are linked to obesity, BDNF may represent the bridge among obesity, depression, and CV diseases." (PMID 35911513, 2022). "Serum BDNF has also been associated with post-stroke depression, and low serum BDNF levels may indicate the development of depression in patients with acute ischemic stroke." (PMID 35177977, 2022). "The occurrence of depression in SLE patients may be predicted by decreased BDNF levels and the elevated levels of autoinflammatory factors (including IL-2 and IL-6) linked to depression, as well as their interaction with gut microbiome." (PMID 36506019, 2022). "Therefore, the assumption that dysregulated levels of BDNF can indirectly, using depression as a mediator, put individuals at higher risk for developing EDs is further confirmed." (PMID 35850718, 2022). "Mesolimbic BDNF-TrkB signal transduction is also implicated in the pathophysiology of depressive symptoms, and dysregulation of the mesolimbic DA system is associated with depression-related behaviors." (PMID 35241021, 2022). "It seemed that BDNF Met allele might be protective factor for healthy controls but a risk for PD patients on anxiety or depression personality." (PMID 35815047, 2022). "Interestingly, during a study performed with patients with HIV, it was possible to establish an association between reduced BDNF levels and depression, struggle concentrating, and memory loss." (PMID 35628626, 2022). "Therefore, it is evident that the reduction of BDNF can cause depression-like symptoms in mice whereas the knockout of IDO1 has antidepressant-like effects." (PMID 35711916, 2022).